EIF4E (eukaryotic translation initiation factor 4E)
Diseases named in the same sentence as EIF4E in open-access papers (continued):
Sharing a sentence is not in itself a finding about the gene and the disease.
glioma (continued). "Antitumor effects of merestinib in GBM lines and patient-derived mesenchymal glioma stem cell lines are related to the inhibition of eIF4E phosphorylation and a decrease in global protein synthesis and cyclin D1/D2 translation." (PMID 32340135, 2020). "TMZ, a chemotherapeutic DNA-damaging drug currently used in the standard treatment of GBM, increases eIF4E phosphorylation in glioma cells." (PMID 32340135, 2020). "MNK1 knockdown as well as inhibition by CGP57380 decrease in vitro and in vivo oncogenic activity along with a significant reduction in eIF4E phosphorylation in human glioma cell lines." (PMID 32340135, 2020). "The combination of MNKs and mTORC1 inhibitors further inhibits 4E-BP1 phosphorylation at Ser65, increases eIF4E/4E-BP1 association and inhibits glioma cell protein synthesis and proliferation." (PMID 31795417, 2019). "Levels of eIF4E and its phosphorylated form (p-eIF4E) increase with glioma tumor grade and are predictive of poor survival." (PMID 31795417, 2019). "Our results confirmed enhanced expression of survivin and eIF4E in different glioma cells and increased micro-RNA124 expression in normal human and mouse brain tissue." (PMID 27070093, 2016). "Our published data has shown that cap binding protein eIF4E activated Sox2 translation in glioma stem-like cells." (PMID 27119230, 2016). "Our results demonstrated the significantly increased eIF4E expression in glioma cells, which is consistent with previous results by many other laboratories which showed that eIF4E is overexpressed in many cancers as well as in astrocytic tumours." (PMID 27070093, 2016). "Moreover, borneol has been identified as a sensitizer of glioma cells to radiation, achieved through the induction of autophagy mediated by inhibition of the mTORC1/eIF4E/HIF‐1α regulatory axis." (PMID 39803277, 2025). "In accordance with previous studies, borneol inhibited HIF-1α expression by regulating the mTORC1/eIF4E pathway, and we found that borneol might make glioma cells sensitive to TMZ by promoting HIF-1α autophagic degradation." (PMID 38188151, 2024). "Other studies have shown that TMZ promotes eIF4E phosphorylation by MNK1/2 in glioma cells." (PMID 36994107, 2023). "The EIF4E-Sox2 axis has also been demonstrated to represent a novel mechanism for unmodulated self-renewal of glioma-initiating cells, offering a potential therapeutic target for glioma." (PMID 36998056, 2023). "eIF4E was also upregulated in glioma cell strains than in HBE cells." (PMID 36225177, 2022). "All these suggest the role of eIF4E gene as an attractive potential target for glioma therapy." (PMID 36225177, 2022). "However, there are few studies investigating eIF4E expression and revealing its potential role in glioma." (PMID 36225177, 2022). "Additionally, we measured eIF4E at mRNA and protein levels in clinical samples collected between July 2019 and September 2021, as well as glioma cell strains." (PMID 36225177, 2022). "Thus, the motivation and novelty of this study are to demonstrate eIF4E overexpression and clarify the biological function of eIF4E under OS in glioma cells." (PMID 36225177, 2022). "Furthermore, the expression levels of LC3 and Beclin-1 were also upregulated in the eIF4E-silenced glioma cells (P <0.01)." (PMID 34917504, 2021). "Thus, borneol sensitizes glioma cells to radiation by inducing autophagy via the inhibition of the mTORC1/eIF4E/HIF-1A pathway." (PMID 34917504, 2021). "Furthermore, the combination of borneol and radiation exposure significantly decreased the expression levels of HIF-1α, mTORC1 and eIF4E proteins in the glioma cells compared to the untreated controls (p < 0.05 or p < 0.01)." (PMID 34917504, 2021). "In conclusion, the findings of the present study suggest that HIF-1α may be a key factor in apoptosis of glioma cells, and mTORC1/eIF4E pathway is involved in the HIF-1a expression regulation by borneol in malignant glioma." (PMID 32626528, 2020).
glioma (continued). "In conclusion, the findings of the present study suggest that HIF-1α may be a key factor in borneol induced apoptosis of glioma cells, and mTORC1 / eIF4E pathway is involved in the HIF-1α regulation by borneol in malignant glioma." (PMID 32626528, 2020). "Additional in vitro and in vivo studies support a role for eIF4E in gliomas." (PMID 31795417, 2019). "Since the ICP4 gene was also translationally regulated by the FGF gene 5′ UTR, which requires a high level of eukaryotic translation initiation factor 4 (eIF4E) for successful translation, we performed western blot analysis to measure the eIF4E level in normal neurons and various glioma cells." (PMID 27070093, 2016). "However, it remains to define the correlation of eIF4E gene with glioma progression." (PMID 36225177, 2022). "In addition, this study aims to explore eIF4E gene expression in glioma and its sensitivity to OS." (PMID 36225177, 2022). "Besides, whether eIF4E can regulate the OS sensitivity of glioma in combination with autophagy and other pathways to regulate the apoptosis of glioma cells needs further research." (PMID 36225177, 2022). "Therefore, we hypothesized that borneol induces autophagy in glioma cells by targeting the mTORC1/eIF4E signaling pathway, which in turn downregulates HIF-1α and sensitizes the cells to radiotherapy." (PMID 34917504, 2021). "Previous studies have found that borneol promotes cellular autophagy via the mTORC1/eIF4E/HIF-1α axis, thereby sensitizing glioma cells to radiation." (PMID 38188151, 2024). "Western blot analysis was also performed to detect EIF4E protein expression, one of the key hub genes, after PBK knockdown in the HS683 glioma cell line." (PMID 39649886, 2024). "eIF3C, eIF3D, eIF4E and 4E-BP1 correlated with tumour grade with significantly higher levels in HGG compared to LGG (low grade glioma)." (PMID 37907716, 2023). "H2O2-induced OS can stimulate eIF4E expression in U251 cells, and downregulating eIF4E can prevent H2O2-induced glioma cells from proliferating, invading, and migrating and promote apoptosis." (PMID 36225177, 2022). "While downregulating eIF4E decreased the ROS level, it promoted H2O2-induced apoptosis of glioma U251 cells." (PMID 36225177, 2022). "The expression levels of eIF4E and HIF-1 α in primary human glioma cells transfected with mTORC1 siRNA were detected by immunofluorescence." (PMID 32626528, 2020). "Immunohistochemistry analysis showed that EIF4E, EIF4E3, and NCBP2 were increased in lower-grade glioma tissues, while lower-grade glioma did not cause a significant difference in EIF4E2 and NCBP1 proteins." (PMID 36998056, 2023). "Furthermore, Ribavirin modulates EZH2, Snail, and eIF4E in nasopharyngeal carcinoma (NPC), osteosarcoma, and glioma leading to decreased migration and adhesion." (PMID 34206772, 2021). "Then, we found that eIF4E siRNA suppressed the expression of HIF-1α, whereas the expression of eIF4E was inhibited by the mTORC1 siRNA, suggesting that the mTORC1/eIF4E pathway participates in regulating the expression of HIF-1α in primary human glioma culture cells under hypoxia." (PMID 32626528, 2020). "Ribavirin shows promising effects against cancer via suppressing eIF4E phosphorylation and activation and leading to decreased mRNA export and protein synthesis in pharyngeal, ovarian, breast cancer, acute lymphoblastic leukemia (ALL), osteosarcoma, and glioma." (PMID 34206772, 2021). "On the other hand, there were no considerable differences in the protein levels of EIF4E, EIF4E3, and NCBP2 between healthy brain tissues and lower-grade glioma tissues." (PMID 36998056, 2023). "In contrast, immunohistochemical analysis of 10 refractory epilepsy tissues and 10 lower-grade gliomas (WHO grade II-III) tissues showed that lower-grade gliomas did not significantly increase in EIF4E2 and NCBP1 protein expression, while EIF4E, EIF4E3, and NCBP2 were increased." (PMID 36998056, 2023).
glioma (continued). "Furthermore, S6K1, but not eIF4E, rescued glioma growth in soft agar from rapamycin-mediated suppression, and transient S6K1 inhibition was sufficient to significantly reduce glioma growth in soft agar." (PMID 22570651, 2012).
non-small cell lung carcinoma (13 papers, 2009 to 2024). A group of at least three distinct histological types of lung cancer, including non-small cell squamous cell carcinoma, adenocarcinoma, and large cell carcinoma. "This is in contrast to previous observations in cancers, such as non-small-cell lung cancer, in which both elevated levels of eIF4E and inactivation of the 4E-BP1 repressor protein are the primary mechanisms for activating the eIF4F complex." (PMID 19603014, 2009). "In non-small-cell lung carcinoma (NSCLC) patients, high levels of MNK2 were observed in the cytoplasm and correlated with phosphorylated eIF4E levels." (PMID 32517051, 2020).
pancreatic cancer (12 papers, 2009 to 2025). "As reported in mouse models of pancreatic cancer and glioblastoma, in well-perfused tumor areas, mTOR and eIF4E are active and their inhibition restricts tumor growth." (PMID 40670359, 2025). "In this line, it has been shown that PHGDH interacts with the translation initiation factors eIF4A1 and eIF4E, supporting the assembly of the complex eIF4F on the 5’ mRNA structure to promote pancreatic cancer progression." (PMID 40640948, 2025). "Next, targeting eIF4E and eIF4A-dependent translation by using specific eIF4A inhibitors in combination with rapamycin shows significant growth inhibition in pancreatic cancer cells." (PMID 36900235, 2023). "The molecular communication by means of the secretome promoted pancreatic cancer cell proliferation, migration and inhibited apoptosis through eIF4E activation." (PMID 30923340, 2019). "Mechanistically, PHGDH interacted with the translation initiation factors eIF4A1 and eIF4E and facilitated the assembly of the translation initiation complex eIF4F to promote the development of pancreatic cancer." (PMID 30744688, 2019). "Our findings show that activated PSCs acquire a pro-inflammatory phenotype and secret proteins that stimulate pancreatic cancer growth in an eIF4E-dependent manner, providing further insight into the role of stromal cells in pancreatic carcinogenesis and cancer progression." (PMID 30923340, 2019). "Besides catalyzing serine synthesis, PHGDH promotes pancreatic cancer development through enhancing the translation initiations by interacting with eIF4A1 and eIF4E." (PMID 30744688, 2019). "Inhibiting PHGDH expression and disrupting the interactions between PHGDH and eIF4A1/eIF4E provide new prospects for anti-tumor therapeutics designs, which are meaningful for improving the pancreatic cancer treatment effect and prolonging the overall survival of clinical patients." (PMID 30744688, 2019). "Additionally, eIF4E increased tumour cell motility and inhibited pancreatic cancer cells apoptosis." (PMID 30923340, 2019). "In pancreatic cancer, PHGDH enhances mRNA translation by interacting with eIF4A1 and eIF4E, thereby promoting cancer development." (PMID 36578934, 2022). "In the case of pancreatic cancers, these include K-ras signaling, invasion, Small GTPase-signaling, apoptosis, integrin signaling, DNA damage control, notch signaling, and JNK signaling – all pathways that converge on eIF4E." (PMID 19401772, 2009).
breast tumor (10 papers, 2009 to 2023). "In vivo animal experiments showed that knockdown of eIF4E expression significantly inhibited breast tumor growth volume, while immunohistochemistry showed that knockdown of eIF4E decreased the expression of the mesenchymal marker vimentin." (PMID 37217473, 2023). "Estimates of eIF4E activity predict sensitivity to mTOR inhibition in cell lines but breast tumours with high estimated eIF4E activity gain changes in eIF4E regulation in order to enhance resistance." (PMID 21320304, 2011). "We have used IHC to determine expression levels in breast tumours of the main regulatory molecules of the eIF4E pathway – namely, eIF4E, 4E-BP1, 4E-BP2 and phosphorylated 4E-BP1 (Thr37/46) (termed p4E-BP1)." (PMID 19367274, 2009). "We have determined expression levels of eIF4E, 4E-BP1, 4E-BP2 and phosphorylated 4E-BP1 within 424 breast tumours, and have carried out analyses to combine these and relate the product to patient survival, in order to estimate eIF4E activity." (PMID 19367274, 2009). "However, although these studies include eIF4E in breast tumors and, more recently the phosphorylation status of this protein, very few studies have addressed the nature of MNK1/2 expression, now considered a potential target for anticancer therapy." (PMID 29568373, 2018). "Therefore, immunohistochemical analysis was performed on over 3000 breast tumors to investigate the relationship among expression of eIF4A1, the helicase-modulating proteins eIF4B, eIF4E and PDCD4, and clinical outcome." (PMID 25611378, 2015). "In an alternative approach we estimated eIF4E activity, a key effector of mTOR function, and tested the hypothesis that eIF4E activity predicts sensitivity to mTOR inhibition in cell lines and in breast tumours." (PMID 21320304, 2011). "Importantly, we also examined whether estimates of pre-treatment eIF4E activity in clinical breast tumours predicted response to the mTOR inhibitor everolimus." (PMID 21320304, 2011). "For example, treatment of breast tumor cells with rapamycin reduces the phosphorylation of the mTOR targets S6K and 4EBP1 while simultaneously increasing the phosphorylation of AKT and eIF4E." (PMID 32758183, 2020). "This may be due to MYC-mediated monopolization of the protein translation machinery and regulation of the translation factors eIF4E, eIF4A, and eIF4G and could explain in part how TA suppresses breast tumor growth in animal models without evidence of toxicity." (PMID 35095503, 2021). "Finally, eIF4E might confer tamoxifen resistance via oestrogen receptor independent pathway due to the activity of mTOR and MNK1, one of the downstream modulators being RUNX2 which is found to be important in breast tumour growth and metastasis." (PMID 32066877, 2020).
head and neck cancer (10 papers, 2009 to 2024). A primary or metastatic malignant neoplasm affecting the head and neck. "Elevated level of eIF4E in tumor-free surgical margins was correlated with local-regional recurrence in patients with head and neck cancer." (PMID 23762622, 2012). "Some studies have demonstrated that expression levels of mTOR and downstream targets eIF4E, 4EBP1, S6K1, and S6 are potential diagnostic and prognostic biomarkers for head and neck cancer." (PMID 23762622, 2012). "Antisense RNA therapy of eIF4E might be used as an adjuvant treatment for head and neck cancer, especially when eIF4E was found to be elevated at the surgical margin." (PMID 37601696, 2023). "In addition, expression levels of mTOR and downstream targets eIF4E, 4EBP1, S6K1, and S6 are potential diagnostic and prognostic biomarkers for head and neck cancer." (PMID 23762622, 2012). "In addition, mTOR and downstream targets eIF4E, 4EBP1, S6K1, and S6 are potential diagnostic and prognostic biomarkers for head and neck cancer." (PMID 23762622, 2012). "Furthermore, eIF4E expression is elevated during hypoxia, and at the invasive front in head and neck cancer and in invasive disease." (PMID 19134194, 2009).
nasopharyngeal carcinoma (10 papers, 2014 to 2022). A carcinoma arising from the nasopharyngeal epithelium. "Interestingly, in nasopharyngeal carcinoma (NPC), astrocytoma, and epithelial ovarian cancer tissues, immunohistochemistry (IHC) was used to show expression of MNK1 or phospho-MNK1 in the nuclei, whereas phospho-eIF4E was more readily observed in the cytoplasm." (PMID 32517051, 2020). "There is an overexpression of p-eIF4E and p-MNK1 in nasopharyngeal carcinoma (NPC) compared to non-cancerous nasopharyngeal epithelial tissues, which is associated with lymph node metastasis and poor survival." (PMID 32340135, 2020).
head and neck squamous cell carcinoma (9 papers, 2009 to 2025). A squamous cell carcinoma that arises from any of the following anatomic sites: lip and oral cavity, nasal cavity, paranasal sinuses, pharynx, larynx, and salivary glands. "Moreover, allosteric mTOR inhibitors can modestly reduce phosphorylated 4E-BP1 levels by inhibiting its phosphorylation and, as a result, are unable to effectively inhibit eIF4E-mediated cap-dependent translation initiation in human cancers, including head and neck squamous-cell carcinomas." (PMID 40563640, 2025).
lymph node metastasis (9 papers, 2010 to 2023). "Further analysis showed that eIF4E was closely associated with the depth of invasion, lymph node metastasis and clinical stages." (PMID 27907907, 2016). "We found that higher expression of p-Mnk1 and p-eIF4E is associated with the cervical lymph node metastasis in NPC." (PMID 24551240, 2014). "Most importantly, NSCLC patients with lymph node metastasis had significantly elevated expression of p-Akt, p-mTOR and p-eIF4E (all P<0.05)." (PMID 32023262, 2020). "Most importantly, positive expression of p-Akt, p-mTOR and p-eIF4E in NSCLC patients with lymph node metastasis (LNM) was significantly higher than those without LNM (P = 0.033, P = 0.025 and P = 0.036, respectively)." (PMID 32023262, 2020). "Our results indicated that expression of p-Mnk1 and p-eIF4E protein in the NPC patients with cervical lymph node metastasis was significant higher than those without lymph node metastasis." (PMID 24551240, 2014). "The expression of p-Mnk1 and p-eIF4E in NPC was proved to be the independent prognostic factors regardless of lymph node metastasis, clinical stages and combination of radiotherapy and chemotherapy, histological type, age and gender by multivariate analysis." (PMID 24551240, 2014). "The eIF4E positive expression in lymph node metastasis group was significantly higher than that in no-lymph node metastasis." (PMID 21159249, 2010). "The positive expression of p-eIF4E and p-Mnk1 in the NPC with cervical lymph node metastasis was significantly higher than those without lymph node metastasis." (PMID 24551240, 2014).